SMAD4 (SMAD family member 4)
Diseases named in the same sentence as SMAD4 in open-access papers (continued):
Sharing a sentence is not in itself a finding about the gene and the disease.
pulmonary fibrosis (23 papers, 2017 to 2025). Chronic progressive interstitial lung disorder characterized by the replacement of the lung tissue by connective tissue, leading to progressive dyspnea, respiratory failure, or right heart failure. "We identified over 2,500 O-GlcNAc modified proteins including α-SMA, TIMP1, TIMP3, Smad4, Smad5 and Smad3 have been implicated in pulmonary fibrosis." (PMID 38665916, 2024). "Hypermethylation of mothers against decapentaplegic homolog 4 (Smad4) also drives pulmonary fibrosis and elevates the susceptibility to pulmonary carcinogenesis in IPF." (PMID 38915445, 2024). "However, Zhang and his colleagues have found that ARDS-associated pulmonary fibrosis might ameliorate through the SMAD4 signaling pathway." (PMID 34803679, 2021). "In our study, we demonstrate the anti-fibrotic potential of NCI-41356 as a new chemical inhibitor of HSPB5/SMAD4 interaction in a bleomycin-induced pulmonary fibrosis model." (PMID 37259327, 2023). "Smad proteins were the main signal transducers of the TGF-β signaling pathway, in which Smad3 binds to Smad4, forms a complex and enters the nucleus to regulate the targeted gene transcription, which thereby interferes with the formation of lung fibrosis." (PMID 33953686, 2021). "Smad3 and Smad4 proteins were overexpressed in BLM-induced pulmonary fibrosis rats compared with normal rats." (PMID 33953686, 2021). "It has been demonstrated that SARS-CoV N protein potentiate Smad-3 mediated TGF-β activation, and plasminogen activator inhibitor-1 (PAI-1), leading to severe pulmonary fibrosis and inactivation of pro-apoptotic genes by complex formation of Smad3 and Smad4." (PMID 32512929, 2020). "Furthermore, in vitro experiments in lung tissue and lung epithelial A549 cells revealed that ginkgolic acid inhibited the TGF-b1-mediated SUMOylation of SMAD4 and epithelial–mesenchymal transition, thus achieving protective effects against pulmonary fibrosis." (PMID 36558920, 2022). "In conclusion, our results revealed that miR‐34a could inhibit EMT in pulmonary fibrosis via targeting SMAD4." (PMID 32929850, 2020). "This might be the process which explains the involvement of SMAD4 in the occurrence and progression of pulmonary fibrosis." (PMID 29997685, 2018). "Among these miRNAs, miR-26a has been shown to suppress the expression of mothers against decapentaplegic homolog 4 (Smad4) and connective tissue growth factor (CTGF) and has been reported to have protective effects against lung fibrosis." (PMID 41323794, 2025). "Conversely, depletion of TRIM33 leads to increased production of TGF-β1, inducing idiopathic pulmonary fibrosis (IPF) and interstitial lung inflammation through Smad4 and downstream inflammatory factors such as TNF-α and IL-6." (PMID 37415133, 2023). "After TGF-β1 stimulation of cells, Smad2/3 and Smad4 aggregated to form protein complexes that entered the nucleus and thus promoted ECM production and aggravated pulmonary fibrosis." (PMID 37416778, 2023). "Ginkgolic acids can reduce pulmonary fibrosis both in vitro and in mouse models through the inhibition of the TGF-b1-mediated SUMOylation of SMAD4 and epithelial–mesenchymal transition." (PMID 36558920, 2022). "Our data show that the increased β2M expression is mediated by the TGF-β1/Smad4/a-SMA pathway, resulting in alveolar epithelial cell EMT, alveolar wall/septal thickening, pulmonary fibrosis, and decreased DLCO values." (PMID 33472168, 2020). "Moreover, HSPB5 interacts with SMAD4 and stabilizes the complex SMAD2/3/4 in the nucleus, thus promoting TGF-β1 signaling and subsequent lung fibrosis." (PMID 37259327, 2023). "We demonstrated that NCI-41356 was able to disrupt the nuclear interaction of HSPB5 and SMAD4 in a fibrotic context, thus limiting the translocation of SMAD4 and his partner pSMAD3 into the nucleus and leading to the inhibition of TGF-β1 signaling in vitro and lung fibrosis in vivo." (PMID 37259327, 2023).
pulmonary fibrosis (continued). "One of the most abundant antifibrotic miRNAs is miR-27a, and lentiviral delivery of miR-27a-3p has been reported to reduce BLM-induced pulmonary fibrosis by targeting the phenotypic marker of myofibroblasts, alpha-smooth muscle actin (α-SMA), and two key Smad transcription factors, Smad2 and Smad4." (PMID 31949877, 2019). "Interestingly, previous studies have shown that upregulation of HSPB5 expression in idiopathic pulmonary fibrosis (IPF) can reduce the expression of TRIM33 and weaken the interaction between TRIM33 and Smad4, thus hindering the ubiquitination and nuclear output of Smad4." (PMID 35333698, 2022). "The complex interactions between TRIM33, Smad4, and the small heat shock protein B5 (HSPB5) may represent key targets in the prevention of the progression of fibrosis in cases of induced lung fibrosis, as in iatrogenic diseases or in idiopathic pulmonary fibrosis." (PMID 37185726, 2023). "SMAD4 and SMAD7 have a regulating activity to SMAD2/3 and play a significant regulatory role in pathophysiological processes such as skin healing and pulmonary fibrosis; however, NAM showed no obvious effect on the protein expression of SMAD4 and SMAD7 at 28 dpi." (PMID 38973179, 2024).
colorectal tumors (22 papers, 2002 to 2025). "A review of SMAD4-mutated colorectal tumors similarly reported more frequent mutations among colon versus rectal tumors, but did not differentiate between proximal and distal colon." (PMID 41413856, 2025). "Whole genome sequencing of these mouse tumor-derived organoids (MTDOs) confirmed the presence of classical colorectal tumor Apc mutations and SMAD-4 stop and frameshifting mutations." (PMID 38473429, 2024). "Development of colorectal tumors with loss of function mutations in the tumor-suppressor gene Smad4." (PMID 37174036, 2023). "Inactivating SMAD4 mutations occur in approximately 10 to 16% of colorectal tumors, similar to the 14% frequency of mutated cases appearing in our cohort." (PMID 36497403, 2022). "Studies in compound mutant mice (Apc−/− and Smad4−/−) indicate that mutations in Smad4, which encodes a protein involved in TGFβ signaling, play a significant role in malignant progression of colorectal tumors." (PMID 24244446, 2013). "Mutations in SMAD4 have been reported in human pancreatic and colorectal tumors." (PMID 29564063, 2018). "SMAD4-mediated bone morphogenetic protein (BMP) signaling inhibits intestinal tumorigenesis, whereas SMAD4-independent BMP signaling promotes metastasis in colorectal tumors." (PMID 40142219, 2025). "Specifically, miR‐495‐3p acts as a tumor suppressor in colorectal tumors by negatively regulating key genes involved in cell cycle progression, including TGFβR1, TGFβR2, SMAD4, and BUB1." (PMID 40620190, 2025). "In this study, we found that the simultaneous deletion of SETD2 and SMAD4 in mice led to an increased number and size of colorectal tumours and reduced survival rates, aligning with clinical data." (PMID 37962020, 2023). "From somatic studies, SMAD4 is not seen to be a driver gene for GI cancer, though 16% of primary colorectal tumours have alterations in SMAD4, and 6% in SMAD2." (PMID 38066625, 2023). "Supporting this view, RAB10 expression is increased in colorectal tumors that have deep deletions of SMAD4 as compared with tumors with gain of SMAD4." (PMID 37377893, 2023). "Despite the majority of CRCs having deactivating TGF‐β pathway mutations (TGFBR1, TGFBR2, SMAD4, SMAD2, SMAD3), colorectal tumours produce significant amounts of TGF‐β, creating a TGF‐β rich environment, to which only the stromal compartment can respond." (PMID 35595718, 2022). "Smad4‐mediated BMP signaling inhibits intestinal tumorigenesis, while Smad4‐independent BMP signaling promotes metastasis in colorectal tumors." (PMID 35274815, 2022). "In order to evaluate the clinical relevance of SMAD4 deletion, gene copy alterations were determined by copy dosage using real-time quantitative PCR in 202 colorectal tumour biopsies from a previous randomised study of adjuvant chemotherapy." (PMID 12237773, 2002). "At the clinical level, TCGA analysis shows that RAB10 is significantly less expressed in colorectal tumors with a gain of SMAD4 as compared with tumors with deep deletion of SMAD4 (*, P = 0.0391 gain vs. deep deletion), suggesting that RAB10 expression is upregulated in absence of SMAD4." (PMID 37377893, 2023). "Importantly, our analyses revealed that, while known CRC driver genes APC and SMAD4 were disrupted in both human colorectal tumors and tumors from ApcMin/+ mice, the questionable MCC gene was disrupted in human tumors but appeared to be intact in mouse tumors." (PMID 20707908, 2010).
colorectal tumors (continued). "Nevertheless, the reason for the overexpression of Smad4 in early colorectal tumour tissues remains unknown." (PMID 15785755, 2005). "Thus, the frequent deletion of the chromosomal region 18q21 in colorectal tumours together with the physiologic functions of TGFβ strongly suggested a role for SMAD4 in the suppression of colorectal carcinogenesis." (PMID 12237773, 2002). "The profound downregulation of TGF-β signaling in human IEC cell lines may be explained by the fact that TGFBRII mutations are highly represented in tumors with microsatellite instability and SMAD4 is mutated in more than half of colorectal tumors without microsatellite instability." (PMID 29977289, 2018). "Moreover, we observed that Smad4-negative pancreatic and colorectal tumours contain fewer stromal S100A8-positive monocytes than their Smad4-positive counterparts, suggesting a regulated relationship between cancer cells and surrounding monocytic cells." (PMID 30558665, 2018).
bladder cancer (21 papers, 2012 to 2025). "Abundant studies have proven that SMAD4 loss can promote tumor progression in different types of tumors, including bladder cancer." (PMID 36856518, 2023). "The observed regulation of the SMAD4/C-MYC/Cyclin D1 axis by miR-146b underscores its potential as a key modulator in bladder cancer progression." (PMID 40224178, 2025). "Our findings provide novel insights into the role of miR-146b in regulating the SMAD4/C-MYC/Cyclin D1 axis in bladder cancer, aligning with previous studies demonstrating miR-146b’s oncogenic potential in various malignancies." (PMID 40224178, 2025). "In bladder cancer, SMAD4 overexpression decreased bladder cancer cell proliferation, migration, and invasion abilities." (PMID 40224178, 2025). "LncRNA AWPPH strengthens cell proliferation, migration and autophagy in bladder cancer by down-regulating SMAD4." (PMID 34176471, 2021). "High expression of Smad2 and Smad4 in the TGF-β signaling pathway predicts longer OS in bladder cancer patients, while TGF-β1 is inversely correlated with the survival rate." (PMID 34141706, 2021). "In bladder cancer, miR-182 promotes the cell proliferation, migration and invasion by suppressing Smad4 and RECK." (PMID 24884732, 2014). "Since loss of Smad4 has been reported to play a causal role in initiating squamous cell carcinomas of the skin, upper digestive tract as well as adenocarcinoma of the gastrointestinal tract, our results may indicate that Smad4 plays an important role in bladder cancer." (PMID 23226455, 2012). "In conclusion, our data suggests that miR-182-5p plays an important role as an oncogene by knocking down RECK and Smad4, resulting in activation of the Wnt-beta-catenin signaling pathway in bladder cancer." (PMID 23226455, 2012). "In our study, Smad4 overexpression decreased bladder cancer cell proliferation, migration and invasion ability." (PMID 23226455, 2012). "Cell viability, invasion and migration were significantly inhibited in RECK and Smad4 transfected T24 bladder cancer cells." (PMID 23226455, 2012). "Apoptosis was also increased with Smad4 overexpression in bladder cancer cells." (PMID 23226455, 2012). "Furthermore, increased MIR4435-2HG expression level was observed in bladder cancer, and could promote cell proliferation and migration by inhibiting SMAD4." (PMID 30972258, 2019). "In this study, we propose that miR-146b-induced repression of SMAD4 leads to enhanced C-MYC expression and subsequent upregulation of Cyclin D1, facilitating the rapid growth and metastasis of bladder cancer cells." (PMID 40224178, 2025). "The results indicated that SMAD4 and FOXO1 were down-regulated in bladder cancer tissues compared to normal tissues (p < 0.05)." (PMID 36856518, 2023). "It was confirmed that miR-5195-3p inhibited the proliferation and invasion of bladder cancer cells by targeting the oncogene KLF5.21 and inhibited the activity of HCT116 cells by inhibiting the expression of TGFβR1, TGFβR2, SMAD3 and SMAD4." (PMID 37328795, 2023). "Data identified that in the low HER2 cohort and different ATM levels (high/low); ABL1, SMAD4, RB1 and PARP1 were significantly upregulated and AKT1, AKT2, TSC2, RPTOR and mTOR were significantly downregulated in bladder cancer." (PMID 36056635, 2022). "Tumor Suppressor Role of SMAD4: AWPPH worked synchronously with EZH2 and epigenetically inactivated SMAD4 to promote proliferation and migration of bladder cancer cells." (PMID 33511320, 2021). "While in bladder cancer miR-182-5p can regulate the expression levels of Smad4 and RECK, and high-expression of miR-182-5p can significantly shorten the overall survival of bladder cancer patients." (PMID 32102688, 2020). "Taken together, this study shows that miR-182-5p exerts its oncogenic effects in bladder cancer cells by down-regulating RECK and Smad4." (PMID 23226455, 2012).
bladder cancer (continued). "Other miRNAs and transcription factors could also influence the expression of SMAD4, C-MYC, and Cyclin D1, further modulating bladder cancer cell growth and proliferation." (PMID 40224178, 2025). "This is the first report to also document that miR-182-5p expression is significantly increased in bladder cancer tissues where it functions as an oncogene by inhibiting RECK and Smad4 expression and may be potentially useful as a prognostic biomarker." (PMID 23226455, 2012). "Finally, we over-expressed these target genes (Smad4 and RECK) in bladder cancer cells to examine the mechanism of miR-182-5p function." (PMID 23226455, 2012). "Consistent with this notion, this research group found that SENP2 could desumoylates TGF-β RI receptor but not Smad4 in bladder cancer cells." (PMID 29955155, 2018).
lymph node metastasis (21 papers, 2007 to 2026). "A meta-analysis revealed that SMAD4 mutations were well associated with overall, progression-free, and relapse-free survival and several clinicopathological parameters, including lymph node metastasis." (PMID 36142267, 2022). "For tumors with two SMAD4 alleles there was only a significant difference between lymph node metastasis and hepatic metastasis." (PMID 33509126, 2021). "SMAD4 mutations are associated with lymph node metastases, increased angiogenesis, and more aggressive cellular behavior in vitro." (PMID 33643409, 2020). "Loss of SMAD4 expression in CRCs is associated with advanced-stage disease, presence of lymph node metastasis, and poor prognosis." (PMID 28423626, 2017). "Associations between the cytoplasmic expression of RhoT1, Smad4, p16 and the presence of lymph node metastasis and perineural invasion." (PMID 22860091, 2012). "Upregulation of Smad2 and Smad4 proteins were also significantly correlated with lymph node metastasis, distant metastasis, advanced stage, and poor survival (p < 0.0001)." (PMID 35456495, 2022). "We also found that the serum concentration of Smad4 was negatively correlated with the degree of lymph node metastasis and that the serum Smad4 in patients with late clinical stage was lower than that in patients with early clinical stage." (PMID 33794845, 2021). "This meta-analysis suggests that SMAD4 mutation was associated with OS, PFS/RFS, and clinicopathological parameters, including tumor site, disease stage, RAS status, lymph node metastasis and mucinous differentiation." (PMID 34301194, 2021). "The serum concentration of Smad4 was negatively correlated with the degree of lymph node metastasis of NSCLC (N0–N1: 157.67 ± 26.65 ng/L; N2–N3: 88.24 ± 15.28 ng/L) (P < 0.001)." (PMID 33794845, 2021). "c NSCLC patients with lymph node metastasis (N2–N3) had a lower Smad4 expression than patients with lymph node metastasis (N0–N1) (P = 0.010)." (PMID 33794845, 2021). "Kaplan-Meier Plotter Database (202527_s_at) analysis of overall survival and survival with lymph node metastasis indicated that lower expression of Smad4 in GC tissues resulted in a shorter survival period." (PMID 33172486, 2020). "Low SMAD4 expression significantly correlated with the clinical stage (P = 0.004), tumor size (P = 0.020), and lymph node metastasis (P = 0.041)." (PMID 31867281, 2019). "Remarkably, SMAD4 and AKR1B1 hypermethylation exhibited a significant association with invasive duct carcinoma (IDC), particularly in early stages, high grades, and cases with lymph node metastasis." (PMID 41760667, 2026). "Similarly, in non-small-cell lung carcinoma, SMAD4 expression has been shown to be higher in normal broncho-tracheal epithelium while lower in tumor tissues and closely correlated with lymph node metastasis." (PMID 38003265, 2023). "In addition, the expression level of Smad4 was decreased in patients with lymph node metastasis and later stage." (PMID 33794845, 2021). "The frequency of SMAD4 LOH was higher in patients with lymph node metastasis, mutations, or both compared to those where no metastasis was observed (P = 0.011)." (PMID 31867281, 2019). "Multivariate analysis showed that lymph node metastasis (relative risk (RR): 2.222, P = 0.014), negative Smad4 IHC labeling (RR: 0.269, P < 0.001) and negative P16 IHC labeling (RR: 0.360, P < 0.001) were independent predictors of OS." (PMID 25890228, 2015). "Negative Smad4 labeling was associated with tumor size, lymph node metastasis, differentiation, and pathological stage, and patients with Smad4 negative specimens had worse OS." (PMID 25890228, 2015). "SMAD4 loss was not correlated with the size, grades, and lymph node metastasis of PDAC." (PMID 28053288, 2017).